IRF3 (interferon regulatory factor 3)
Diseases named in the same sentence as IRF3 in open-access papers (continued):
Sharing a sentence is not in itself a finding about the gene and the disease.
viral infection (continued). "Our model that MAVS signals through multiple TRAF proteins is further supported by mutagenesis experiments which showed that mutations of both TRAF2/5 and TRAF6 binding sites of MAVS, but not each alone, abolished IRF3 and IKK activation by virus infection." (PMID 23951545, 2013). "Previous studies have reported that an absence of IRF-3 in vivo does not profoundly reduce the levels of type I IFN in serum after WNV or other viral infections." (PMID 19798431, 2009). "The most likely candidate would be the constitutively expressed interferon regulatory factor 3 (IRF-3), that is known to be simultaneously activated with NF-κB upon virus infection directly via the RIG-I RNA sensing pathway without the need of type I IFN." (PMID 18989459, 2008). "Furthermore, under the following conditions: without viral infection, during VSV infection, and during NDV infection, overexpression of bat TBK1 all enhanced IRF3-mediated upregulation of IFNβ expression." (PMID 40791583, 2025). "Again, the lack of increase of the IRF3 phosphorylation and nuclear translocation observed in the presence of MSA-2 in 229E infected cells seems to suggest that viral infection can alter MSA-2 efficacy and requires further investigation to be better understood." (PMID 38969014, 2024). "IRF3, IRF7, and IFNB1, which are upregulated naturally in response to viral infection, could not stimulate an immune response due to the activation of the P viral protein." (PMID 27872612, 2016). "As expected, acetate lost the capacity to enhance IFN-I production and IRF3 phosphorylation in Mavs−/− BMDM, nor to protect against IAV infection in Mavs−/− mice, demonstrating that MAVS was indeed involved in the mechanism by which acetate protected the mice from viral infection." (PMID 36746963, 2023). "Here, we reported that epigenetic remodeler ARID1A, a critical component of the mSWI/SNF complex, could bind IRF3 and then was recruited to the Ifn-I promoter by IRF3, thus selectively promoting IFN-I but not TNF-α, IL-6 production in macrophages upon viral infection." (PMID 34315861, 2021). "TBK1 and IKKε were spatially separated from VP35 upon infection by EBOV trVLPs, and IRF3 itself was demonstrated not to interact with VP35 and NP, implying that other IRF3-interacting proteins might be involved in IRF3 sequestration in IBs upon viral infection." (PMID 38285487, 2024).
COVID-19 (44 papers, 2020 to 2026). A disease caused by infection with severe acute respiratory syndrome coronavirus 2. "Increased MCP-1 has been shown to be significantly and negatively correlated with the inhibition of interferon regulatory factor 3 (IRF3) pathway in patients with severe COVID-19." (PMID 39633683, 2024). "Comparison with published pre-vaccine fatal COVID-19 transcriptomic and genomic signatures uncovered a unique IRF3 low/IRF7 high immune signature in post-vaccine fatal COVID-19 outbreaks." (PMID 37217661, 2023). "Regarding antiviral immune response, we observed elevated mRNA expression of RIG-I, MAVS, and IRF-3 in COVID-19 patients evidencing intracellular recognition of the virus." (PMID 35173744, 2022). "While healthy and mild COVID-19 monocytes significantly increased the expression of the phosphorylated form of IRF3 upon LPS stimulation compared to baseline levels, monocytes from moderate patients did not." (PMID 36572683, 2022). "Consistent with this, rare pathogenic variants in TLR7 and eight candidate loci, including, TLR3, IRF3, and IRF7 governing type I IFN response have been identified in patients with critical COVID-19." (PMID 36143338, 2022). "In particular, autosomal-recessive deficiencies in IRF7 and IFNAR1 and autosomal-dominant deficiencies in TLR3, TBK1, IRF3, IRF7, IFNAR1 and IFNAR2 genes have been found in a small percentage of patients with severe influenza and COVID-19." (PMID 35846766, 2022). "The inflammatory mediator of EN-RAGE encoded by S100A12 was significantly correlated with COVID-19, and S100A8, S100A9, IRF3, IFI6, IFITM1, and IFITM3 have been reported to elicit autoinflammatory and autoimmune conditions in response to SARS-CoV-2 infection." (PMID 35172892, 2022). "Another important finding is increased IRF3 levels in villous CTs and chorion EVTs in COVID-19 exposed placentas." (PMID 36743911, 2022). "This gene signature was functionally confirmed by examining the activation pattern of IRF3 in response to LPS in monocytes from healthy individuals and patients with mild and moderate COVID-19." (PMID 36572683, 2022). "We next explored the expression level of IRF3, an important gene in the interferon signaling pathway, in mild COVID-19 patients." (PMID 33413449, 2021). "Our results demonstrated a negative correlation between MCP-1 level in peripheral blood and IRF3 expression level in PBMCs from mild COVID-19 patients in Shiyan City." (PMID 33413449, 2021). "Our findings illustrating increased IRF7 and IRF3 mRNA levels in COVID-19 patients with mild/moderate disease further confirm their role in the host antiviral response." (PMID 33780352, 2021). "Expression of IRF3 was downregulated (0.67 ± 0.35 in mild COVID-19 patients vs 1.12 ± 0.21 in healthy controls; P < 0.01)." (PMID 33413449, 2021). "Next, we measured the individual phosphorylation of STAT3, STAT1, JNK, p38, and IRF3 proteins and found them all to be increased in COVID-19 neutrophil whole cell lysates; however, it should be noted that the total levels of these proteins were not evaluated." (PMID 33003471, 2020). "The best predictive models for mortality comprised IFNB1 or age, viral ORF7a and ACE2 receptor transcripts, whereas comparison with pre-vaccine fatal COVID-19 signatures uncovered a unique IRF3 low/IRF7 high immune signature in post-vaccine fatal COVID-19 outbreaks." (PMID 37217661, 2023). "In another work, TLR-3, IRF3, and IRF7 variants were detected in patients with severe COVID-19." (PMID 35062298, 2022). "SARS-CoV-2 infection also increases the expression of TLR2 and other molecules, such as melanoma differentiation-associated gene 5 (MDA5), ACE2 and interferon regulatory factor 3 (IRF3), and the expression of TLR2 is positively associated with the severity of COVID-19." (PMID 35832809, 2022). "Interestingly, here we noticed an upregulation of RIG-1, MDA5 and IRF3 with VitD treatment in vitro, and in whole blood and saliva of VitD treated COVID-19 hospitalized patients." (PMID 36273032, 2022).
COVID-19 (continued). "Moreover, a comparative study of COVID-19 and influenza showed the activation of STAT3/NF-κB in PBMCs of patients infected with influenza A virus (IAV)- vs. the activation of STAT1/IRF3 in COVID-19 patients." (PMID 34394120, 2021). "nsp3 catalyzes the reaction that preferentially cleaves ubiquitin-like interferon-stimulated gene 15 (ISG15) protein from interferon factor 3 (IRF3) which weakens the type I interferon response, could exacerbate hyperinflammatory conditions and progression to severe COVID-19." (PMID 36318347, 2022). "It has been found that about 3.5% of COVID-19 patients had known autosomal-recessive (AR) deficiencies [interferon regulatory factor 7 (IRF7) and IFNAR1] and autosomal-dominant deficiencies (AD) [toll-like receptor 3 (TLR3), UNC93B1, TICAM1, TBK1, IRF3, IRF7, IFNAR1, and IFNAR2]." (PMID 34335535, 2021). "It is evident that the SARS-CoV-2 spike and Nsp12/6 proteins attenuate the host’s innate immune responses by suppressing IRF3-induced type 1 IFN production, suggesting the mechanism of immune evasion to facilitate the viral replication and COVID-19 severity." (PMID 39633683, 2024). "A bioinformatics analysis of the single-cell and bulk RNA-seq profiling of COVID-19 patients’ data revealed a significant upregulation of cGAS-STING signalling pathway genes (TMEM173, IRF3, NFKB1, CGAS, IFNAR1, and TBK1) in the lung." (PMID 39459875, 2024). "Pantethine inhibited this increase in MAVS and IRF3 expression in infected cells, as well as that of STING, which controls aberrant type I IFN production and cell death in COVID-19 through c-GAS-STING signaling." (PMID 36754974, 2023). "This inability to activate IRF3 correlated with decreased expression of the interferon-stimulated gene IFITM2, examined in an expanded cohort of healthy, mild and moderate COVID-19 monocytes after stimulation with SARS-CoV-2." (PMID 36572683, 2022). "In patients with mild COVID-19 symptoms, however, MCP-1 was shown to correlate with inhibition of IFN signaling via IRF3 downregulation." (PMID 36526890, 2022). "In this sense, IFN polymorphisms or polymorphisms of the molecules in charge of signaling for their production, such as IRF3, IRF7, TICAM1, TBK1, and STAT2, have also been related to poor prognosis of COVID-19 patients." (PMID 35062298, 2022). "The findings of STING, IRF3, and TLR7 upregulation in different cell-types in villous tissue of COVID-19 exposed placentas suggest that cells at the placental maternal-fetal interface react differently in response to maternal COVID-19 infection." (PMID 36743911, 2022). "Significant upregulation of STING, IRF3, TLR7, MAVS, and IFNβ expression was found in COVID-19 exposed placentas vs. controls (p<0.01 for STING, TLR7, MAVS, and IFNβ, and p<0.05 for IRF3)." (PMID 36743911, 2022). "Further biochemical experiments uncovered SARS-CoV-2 Spike potentiated proteasomal degradation of IRF3, implicating a novel mechanism by which SARS-CoV-2 evades the host innate antiviral immune response to facilitate COVID-19 pathogenesis." (PMID 35083167, 2021). "We found that in mild COVID-19 patients with higher levels of MCP-1, expression of IRF3, an important gene in the interferon signaling pathway, was downregulated." (PMID 33413449, 2021). "They observed that in COVID-19 patients, three signaling pathways were activated: the apoptosis pathway, the signal transducer and activator of the transcription 1 (STAT1) pathway, and the interferon regulatory factor 3 (IRF3) pathway." (PMID 38542251, 2024). "Cleavage of IRF3 and critical modulators of inflammatory pathways (NLRP12 and TAB1) was proven by proteases nsp3 and nsp5 in SARS-CoV-2 infected 293T-ACE2 cells, which was involved in the pathophysiology of COVID-19." (PMID 37801439, 2023).
COVID-19 (continued). "All signaling molecules of the IFN-I downstream pathway and IRFs (i.e., JAK-1, TYK-2, STAT-1, STAT-2, IRF-3, and IRF-7) showed very reduced expression levels in COVID-19 patients with the severe condition compared to healthy individuals at both RNA and protein levels." (PMID 35842705, 2022). "Notably, type I IFNs led to a significant increase in IRF3, ISG15, and IFI6 expressions in convalescent COVID-19 patients compared to healthy controls, suggesting a higher degree of activation." (PMID 35464396, 2022). "Finally, we observed a significant negative correlation between expression levels of interferon (IFN) regulatory factor 3 (IRF3) and serum levels of MCP-1 in mild COVID-19 patients." (PMID 33413449, 2021). "Therefore, we suggest that IFN might be used to treat mild COVID-19 patients following detection of upregulation of MCP-1 and downregulation of IRF3." (PMID 33413449, 2021). "Indeed, the lack or presence of cognate cleavage motifs in IRF3 and NLRP12 homologs presents interesting correlations with the presentation of disease in animal models; our results will enable the development of more effective animal models for severe COVID-19." (PMID 33372854, 2021). "The cleavage of IRF3 could explain the enigmatically blunted type-I IFN response that have been noted at early stages of SARS-CoV-2 infections, while the 3CLpro mediated cleavage of NLRP12 might explain the hyperinflammatory response observed at later stages in severe COVID-19 cases." (PMID 33372854, 2021). "Direct cleavage of IRF3 by NSP3 could explain the blunted Type-I IFN response seen during SARS-CoV-2 infections while NSP5 mediated cleavage of NLRP12 and TAB1 point to a molecular mechanism for enhanced production of cytokines and inflammatory response observed in COVID-19 patients." (PMID 33372854, 2021). "In contrast to STING and IRF3 expression, upregulation of TLR7 was seen in both STs, and CTs in COVID-19 exposed placentas (h and h1) compared to non-COVID controls (c and c1)." (PMID 36743911, 2022).
autoimmune disease (36 papers, 2012 to 2025). A disorder resulting from loss of function or tissue destruction of an organ or multiple organs, arising from humoral or cellular immune responses of the individual to their own tissue constituents. "Previous GWASs have also identified an association between IRF3 and various autoimmune diseases such as RA, T1DM, and SLE." (PMID 37197658, 2023). "Despite the effective function in antiviral immunity, certain IFN-driven autoimmune diseases are caused by unregulated IRF3." (PMID 35055355, 2022). "In a model of autoimmune disease, K63-linked ubiquitination of IRF3 on Lys98 activated IRF3 for its transcriptional function." (PMID 33805458, 2021). "Namely, the ovarian tumor domain-containing deubiquitinase 1 (OTUD1) removes ubiquitin linkages from IRF3 and has been implicated in autoimmune disease as a result." (PMID 33805458, 2021). "Mice which lack either of two enzymes responsible for degradation of DNA, 3′ repair exonuclease 1 (Trex1) and DNaseII, develop spontaneous autoimmune disorders associated with the initiation of IRF-3-dependent cytosolic DNA sensing." (PMID 23251783, 2012). "However, excessive IRF3 activation and type I IFNs production could cause autoimmune disease such as STING-associated vasculopathy of infancy." (PMID 31618847, 2019). "OTUD1 prevented excessive interferon production-induced autoimmune disease by removing K63-Ub on Lys98 of IRF3, thereby dampening IRF3 nuclear translocation and transcriptional activity, which blocked RIG-I-like receptor signaling." (PMID 40469292, 2025). "IRF3 and IRF7 are implicated in various diseases, including cancer, autoimmune disorders, inflammatory diseases, cardiac hypertrophy, psoriasis, bacterial infections, and atherosclerosis." (PMID 39844998, 2025). "Previous studies have indicated the potential involvement of TBK1 in inflammatory and autoimmune diseases, which can promote activation of the NF-κB and interferon regulatory factor 3 (IRF3) pathways, as well as the M1 polarization of macrophages." (PMID 40746530, 2025). "Overall, our study reveals a novel function of indomethacin in controlling type I IFN production by regulating IRF3 nuclear translocation and provides a potential treatment for cytosolic nucleic acid-mediated autoimmune diseases." (PMID 38578631, 2024). "TTN regulates abnormal cGAS-STING signalling pathway activation by modulating the interaction between STING and IRF3, demonstrating significant therapeutic potential for autoimmune diseases and ALI mediated by the cGAS-STING pathway." (PMID 39148120, 2024). "IRF3 and IRF7, which are associated with MyD88-independent pathway of TLR4 signalling, also play crucial roles in development of autoimmune disease or CRSwNP, and these molecules are thought to act as pro-inflammatory transcription factors in these diseases." (PMID 35256715, 2022). "STING has been recognized as an activator of immune responses by TBK1/IRF3 and NF-κB pathways, and it is suggested to play critical roles in host defense, autoimmune diseases, and tumor immunity." (PMID 30595664, 2018). "Several modulatory factors in the TLR signaling pathway including IRF3, IRF7, IRF8, TRIM20, MYD88 and NF-κB1 have been associated with autoimmune disease." (PMID 26794091, 2016). "As a key link in innate immunity, IRF3 plays a wide range of biological functions in many diseases and cellular processes, such as tumorigenesis, metabolic reprogramming, antiviral infection, and occurrence and development of autoimmune diseases (71, –, 75)." (PMID 40488465, 2025). "PARP7 targeting of the IRF3:CBP/p300 transcriptional holocomplex could be harnessed to treat other autoimmune diseases such as systemic lupus erythematosus (SLE)." (PMID 39969510, 2025). "Investigating the interaction mechanism between the ubiquitination of the cGAS-STING pathway and the IRF3/IRF7 pathway may elucidate its significant involvement in autoimmune disorders and antiviral responses." (PMID 40028324, 2025).
autoimmune disease (continued). "Glabridin and Licochalcone B, as the main active ingredients in licorice, showed promising ameliorative effects on autoimmune diseases contributed to Trex1 knockout, and their mechanism of action may be related to affecting the binding of IRF3 with STING." (PMID 38904004, 2024). "Additionally, type I interferons (IFN-α) are key cytokines involved in the innate immune response and are implicated in the pathogenesis of autoimmune diseases, such as SLE, mediated by the IRF3 pathway." (PMID 37771504, 2023). "Previous studies have also indicated that celastrol inhibits interferon response through targeting IRF3 activation and may be an effective treatment for interferon response-dependent autoimmune diseases." (PMID 35359864, 2022). "Additionally, its role in suppressing inflammation points to a potential use against a range of autoimmune diseases, particularly those driven by IRF3 activity." (PMID 34619149, 2021). "Depletion of STING, IRF3, cGAS, or IFN-I receptor in TREX1-deficient mice protects against autoimmune disorders and death, indicating that cGAS–STING–IRF3 axis-regulated IFN-I production is responsible for autoimmune disorder development in TREX1-deficient mice." (PMID 31440232, 2019). "Functional regulation of IRF3 via post-translational modifications, including phosphorylation, ubiquitination, SUMOylation, acetylation, ISGylation, and glutathione peptidation and methylation, has profound biological and physiological effects on antiviral and autoimmune diseases." (PMID 37650650, 2023). "In the context of autoimmune diseases, the ubiquitination of the cGAS-STING pathway can interact with IRF3/IRF7." (PMID 40028324, 2025). "The mediator of IRF3 activation (MITA, also named STING) is critical for immune responses to abnormal cytosolic DNA and has been considered an important drug target in the clinical therapy of tumors and autoimmune diseases." (PMID 36449507, 2022). "In turn, these Hippo pathway molecules mediate the regulation of interferon regulatory factor 3 (IRF3) and IFN-β1 by VGLL3, suggesting that VGLL3 receives signal from the Hippo stress-sensing pathway to activate IFN responses, a key immunological pathway in autoimmune disease." (PMID 38726338, 2024). "The STING signalosome, via the recruitment and activation of the canonical interferon regulatory factor 3 (IRF3) and type I interferon pathways, plays an essential role in the regulation of adaptive immune responses, tissue repair and regeneration, host defense, and autoimmune disorders." (PMID 38970078, 2024). "Given that IRF3 is a common molecule downstream of TLR3, RLRs and intracellular DNA signaling pathways, our study identified a novel mechanism to limit RNA and DNA virus-induced signaling, inflammation and tissue injury and provided new clues for the treatment of autoimmune diseases." (PMID 25763818, 2015).